SNHG20 (small nucleolar RNA host gene 20)
Diseases named in the same sentence as SNHG20 in open-access papers (continued):
Sharing a sentence is not in itself a finding about the gene and the disease.
cervical cancer (7 papers, 2019 to 2024). A primary or metastatic malignant neoplasm involving the cervix. "LncRNAs MEG3, CRNDE, LINP1 and SNHG20 are shown to influence cervical cancer progression and we report G4 specific protein partners for these lncRNAs." (PMID 37628839, 2023). "SNHG20 is highly expressed in cervical cancer and promotes proliferation and invasion of cervical cancer cells through the miR-140-5p/ADAM10/MEK-ERK axis." (PMID 30744670, 2019). "The inhibition of SNHG20 can reduce ADAM10 protein expression, resulting in decreased cervical cancer cell proliferation." (PMID 37176052, 2023). "Similarly, SNHG20 enhanced cell proliferation and invasion via the miR‐140/ADAM10 axis in cervical cancer." (PMID 33089952, 2020).
gastric cancer (7 papers, 2017 to 2021). A primary or metastatic malignant neoplasm involving the stomach. "For example, lncRNA small nucleolar RNA host gene 20 (SNHG20) induces gastric cancer progression via upregulating zinc finger protein X-linked (ZFX) expression by absorbing miR-495-3p." (PMID 32156248, 2021). "Therefore, we conducted this study to investigate the functional significance of SNHG20 in gastric cancer (GC) progression and to explore possible mechanisms underlying its functionality." (PMID 29113337, 2017). "The aim of the study is to investigate the functional significance of SNHG20 involved in gastric cancer (GC) progression." (PMID 29113337, 2017). "Together, these results demonstrated that SNHG20 could enhance gastric cancer cell proliferation and invasion in vitro." (PMID 29113337, 2017). "However, the contribution of small nucleolar RNA host gene 20 (SNHG20) to gastric cancer development remains largely unknown." (PMID 29113337, 2017). "For example, both SNHG20 and PVT1 are related to stomach cancer." (PMID 33318305, 2020).
breast carcinoma (5 papers, 2019 to 2021). "In addition, studies find that SNHG20 regulates breast cancer cell proliferation, migration and invasion in breast cancer through the miR-495 / HER2 axis." (PMID 30744670, 2019). "Additionally, SNHG20 could exert its carcinogenic action in breast cancer, and high level of SNHG20 could facilitate the proliferation, invasion and metastasis of cancer cells via modulating miR‐495/HER2 axis." (PMID 32675944, 2020). "For example, in breast cancer cells, miR-495 was the target of SNHG20, and HER2 was regulated by SNHG20 via miR-495 to increase the ability of invasion and migration of tumor cells." (PMID 34381023, 2021).
lung cancer (5 papers, 2017 to 2024). A malignant neoplasm involving the lung. "SNHG20 has been reported to cause a significant reduction in cancer cell apoptosis in A549 cells, which was consistent with the findings in non‐small cell lung cancer." (PMID 33089952, 2020). "SNHG20 contributes to the proliferation and migration of lung cancer cells by acting as an epigenetic regulator of P21." (PMID 38886753, 2024). "Better understanding of SNHG20 mechanisms in the molecular etiology of lung cancer will be helpful for the development of lncRNA-based diagnostic and therapeutic agents against cancers." (PMID 28981099, 2017).
osteosarcoma (5 papers, 2019 to 2023). A usually aggressive malignant bone-forming mesenchymal neoplasm, predominantly affecting adolescents and young adults. "Recent studies have shown SNHG1, SNHG5, SNHG16, and SNHG20 to be overexpressed in osteosarcoma tissues and play vital roles in promoting tumour progression." (PMID 37278038, 2023). "Present studies have identified that silenced SNHG20 inhibited the proliferation, invasion and induced apoptosis in osteosarcoma via miR-139/RUNX2 axis." (PMID 30846486, 2019). "SNHG20 is up-regulated in osteosarcoma tissues and cells and knockdown of SNHG20 up-regulates the expression of apoptosis-related protein Bax, decreases the expression of Bcl-2, inhibits the activity of caspase-3 and caspase-9, and promotes the apoptosis of osteosarcoma cells." (PMID 30744670, 2019).
prostate carcinoma (5 papers, 2021 to 2025). A carcinoma that arises from epithelial cells of the prostate gland. "It was proved that SHNG20 expression was significantly increased in prostate cancer, and SNHG20 overexpression promoted prostate cancer cell proliferation and invasion and decreased cell apoptosis." (PMID 34302635, 2021). "SNHG20, as a competing endogenous RNA, upregulates DDX17 expression to promote the development of prostate cancer." (PMID 35992805, 2022).
laryngeal squamous cell carcinoma (3 papers, 2020 to 2021). A squamous cell carcinoma that arises from the larynx. "Also, SNHG20 is regarded as vital in many cancers and identified as a subtype-specific prognostic gene for laryngeal squamous cell carcinoma in our previous study using a computational method." (PMID 33318305, 2020).
lung adenocarcinoma (3 papers, 2020 to 2021). A carcinoma that arises from the lung and is characterized by the presence of malignant glandular epithelial cells. "SNHG20 regulated lung adenocarcinoma cell proliferation, invasion and promoted cell apoptosis via miR‐342/DDX49 axis." (PMID 33089952, 2020). "As expected, the expression of SNHG20 was overexpressed in lung adenocarcinoma tissues compared with the paracancerous tissues (P < 0.05)." (PMID 33089952, 2020). "Our findings demonstrate that SNHG20/miR‐342/DDX49 axis plays an important role in lung adenocarcinoma, providing a novel insight into the treatment of lung adenocarcinoma." (PMID 33089952, 2020). "In conclusion, SNHG20 was found to play an oncogenic role in the regulation of lung adenocarcinoma cell proliferation, invasion and apoptosis through targeting miR‐342/DDX49 axis." (PMID 33089952, 2020). "DDX49 was found to have negative connection with miR‐342 expression (P < 0.05), and was positively related to SNHG20 expression in lung adenocarcinoma (P < 0.05)." (PMID 33089952, 2020). "Through tissue verification, the expression of SNHG20 in lung adenocarcinoma has been shown to be related to TNM stage, lymph‐node metastasis and the expression of Ki67." (PMID 33089952, 2020). "All the findings showed that knockdown of SNHG20 inhibited the progression of lung adenocarcinoma." (PMID 33089952, 2020). "SNHG20 regulated lung adenocarcinoma progression, indicating that SNHG20 may be a biomarker of lung adenocarcinoma." (PMID 33089952, 2020). "The aim of our study was to investigate the roles of SNHG20 in lung adenocarcinoma." (PMID 33089952, 2020). "However, the role of SNHG20 in lung adenocarcinoma is still unclear." (PMID 33089952, 2020). "However, the function of SNHG20 in lung adenocarcinoma is unclear." (PMID 33089952, 2020). "SNHG20 and DDX49 were overexpressed, while miR‐342 was lowly expressed in lung adenocarcinoma tissues and cell lines." (PMID 33089952, 2020). "SNHG20 regulates DDX49 expression via sponging miR‐342 to regulate cell proliferation, migration and apoptosis in lung adenocarcinoma." (PMID 33089952, 2020). "Knockdown of SNHG20 by sponging miR-342 and upregulating DDX49 could promote cell apoptosis in lung adenocarcinoma." (PMID 34367998, 2021). "In addition, DDX49 participated in forming the SNHG20/miR-342/DDX49 axis, thereby participating in the positive regulation of lung adenocarcinoma cell proliferation, invasion and apoptosis." (PMID 35096017, 2021). "The expression of SNHG20 has a negative connection with miR‐342 expression in lung adenocarcinoma tissues." (PMID 33089952, 2020). "The expression of SNHG20 had a negative connection with miR‐342 expression in lung adenocarcinoma tissues (P < 0.05)." (PMID 33089952, 2020). "Moreover, SNHG20 expression was also higher in lung adenocarcinoma cell lines A549 (P < 0.05) and H1299 (P < 0.05) than the normal epithelial cell line 16HBE." (PMID 33089952, 2020).
COVID-19 (2 papers, 2021 to 2023). A disease caused by infection with severe acute respiratory syndrome coronavirus 2. "Interestingly, a meta-analysis of transcriptomic data sets from COVID-19 patient samples found that SNHG20 was among the top 10 most significantly upregulated lncRNAs." (PMID 36625663, 2023). "Interestingly we found six lncRNAs (TALAM1, DLEU2, and UICLM CASC18, SNHG20, and GNAS) involved in the protein-coding DEG-lncRNA network; which might be served as potential biomarkers for COVID-19 patients." (PMID 34975833, 2021).
liver cancer (2 papers, 2020 to 2021). An epithelial or non-epithelial malignant neoplasm that arises from the liver. "Recently, more and more lncRNAs have been identified dysregulated in CC and regulating CC progression including XLOC_006390, highly upregulated in liver cancer (HULC), Growth arrest-specific transcript 5 (GAS5), Small nucleolar RNA host gene 20 (SNHG20), etc.." (PMID 32398968, 2020).
lymph node metastasis (2 papers, 2020). "The relationship between SNHG20 expression and lymph node metastasis was evaluated in eight studies containing 534 patients." (PMID 32675944, 2020).
fibrosis (1 paper, 2025). the formation of excess fibrous connective tissue in an organ or tissue in a reparative or reactive process. "A recent study identified that downregulation of SNHG20 in HL-1 cardiomyocytes improved Ang II-induced cardiac fibrosis and hypertrophy, indicating a potential compensatory mechanism in our model." (PMID 41020515, 2025).
Non-alcoholic Fatty Liver Disease (1 paper, 2024). "Furthermore, overexpression of SNHG20 stimulates the activation of STAT6, induces M2 polarization of hepatic KCs, and promotes Non-alcoholic Fatty Liver Disease (NAFLD) progression to HCC." (PMID 38523627, 2024).
pulmonary fibrosis (1 paper, 2025). Chronic progressive interstitial lung disorder characterized by the replacement of the lung tissue by connective tissue, leading to progressive dyspnea, respiratory failure, or right heart failure. "SNHG20, a newly identified lncRNA, has been found to participate in the process of vasculogenic mimicry and was associated with pulmonary fibrosis through the microRNA 490-3p (miR-490-3p)/TGFBR1 axis." (PMID 40443971, 2025).
tumor (28 papers, 2016 to 2025). "They found that SNHG20 deficiency reduced the viability and aggressiveness of tumour cells and stimulated apoptosis." (PMID 33968736, 2021). "Obviously, this association demonstrated that patients with increased SNHG20 expression, were more liable to develop large tumor size (OR = 3.08, 95% CI 2.11–4.51, P = 0.000)." (PMID 32675944, 2020). "Higher SNHG20 expression was significantly associated with advanced tumor, lymph node and metastases (TNM) stage and tumor size, as well as poorer overall survival." (PMID 28981099, 2017). "Previous research showed that SNHG20 is highly expressed in NSCLC and can interact with the enhancer of histone methyltransferase 2 to drive P21 expression, thereby inhibiting apoptosis and promoting tumor proliferation and invasion, suggesting that SNHG20 is closely associated with NSCLC." (PMID 38077434, 2023). "In addition, we identified that there was a strong link between SNHG20 overexpression and unfavorable DFS/RFS/PFS, meaning that cohorts with elevated SNHG20 expression exhibited a higher risk of tumor relapse or progression." (PMID 32675944, 2020). "In recent studies, small nucleolar RNA host gene 20 (SNHG20) was found to play oncogenic roles in many tumours." (PMID 38886753, 2024). "SNHGs are a family of lncRNAs derived from snoRNAs, and SNHG1, SNHG5, and SNHG20 have been reported to participate in tumor prognosis in various cancers." (PMID 38553452, 2024). "In gastric cancer patients, SNHG20 is correlated with the size of the tumor, lymphatic metastasis, and a lower overall survival rate." (PMID 36770654, 2023). "SNHG20 interacts with has-miR-331-3p to activate Her2 in tumors, enhancing tumor cell invasion and migration." (PMID 35785035, 2022). "Our data suggested that, compared with the adjacent non-tumor tissues, SNHG20 was dramatically upregulated in the OSCC tissues." (PMID 34282711, 2021). "The SNHG20/EZH2/E-cadherin pathway was also identified as the potential mechanism in promoting tumor progression and epithelial-mesenchymal transition." (PMID 34888264, 2021). "In order to further validate the regulatory role of SNHG20 in OC growth in vivo, we conducted the tumor xenograft assay." (PMID 34836544, 2021). "In total, six studies with 478 patients were employed to disclose a link between SNHG20 expression and tumor size." (PMID 32675944, 2020). "Further molecular mechanism experiments have shown that Snhg20 significantly promotes the proliferation of various tumor cells, indicating that Snhg20 is a positive regulator of tumor cell proliferation." (PMID 32599940, 2020). "This showed that the patients with augmented SNHG20 expression tended towards high tumor stage (OR = 4.51, 95% CI 2.17–9.37, P = 0.000)." (PMID 32675944, 2020). "Results showed that SNHG20 expression was up‐regulated in 12 pairs of OSCC tissue compared with adjacent non‐tumour samples." (PMID 30394668, 2019). "In vitro and in vivo, loss‐of‐function experiments showed that lncRNA SNHG20 knockdown inhibited proliferative ability, mammosphere‐forming ability, ALDH1 expression, stem factors (LIN28, Nanog, Oct4, SOX2) and tumour growth." (PMID 30394668, 2019). "Earlier studies also prove SNHG20 as tumor-suppressive gene in other tumors consistent with our findings." (PMID 30744670, 2019). "The results indicated that SNHG20 expression in tumor tissues was markedly higher than that in adjacent non-tumor tissues (P < 0.001)." (PMID 27543107, 2016). "Univariate analysis showed that patients with depth of invasion (P = 0.040), distant metastasis (P < 0.001), tumor differentiation (P = 0.039), and high SNHG20 (P < 0.001) expression had markedly shorter overall survival." (PMID 27543107, 2016). "Interestingly, the analysis revealed that Meg3, MIAT and SNHG20 are primarily expressed by cells localized at the tumor edge or infiltrating the tumor core." (PMID 40527978, 2025).
tumor (continued). "Furthermore, the impairment of SNHG20 impeded activation of the Wnt/β-catenin pathway and thereby inhibited tumour progression." (PMID 33968736, 2021). "We found that the tumor growth was markedly inhibited by SNHG20 silencing." (PMID 34836544, 2021). "Additionally, we found that miR-148a inhibitor partly reversed the anti-tumor roles of down-regulation of SNHG20 in OC cells." (PMID 34836544, 2021). "We aimed at exploring the relationship between SNHG20 expression levels and prognosis of human carcinomas in the present comprehensive meta-analysis, which pooled a total of 15 independent studies with 1187 tumor sufferers." (PMID 32675944, 2020). "The expression of SNHG20 has a trend of relationship with tumor size, which we speculate is due to the small sample size." (PMID 33089952, 2020). "Consistently, overexpression of SNHG20 could promote cell-cycle, proliferation, invasion, and migration of tumor cells via different mechanisms, while up-regulated SNHG20 is an unfavorable prognostic factor." (PMID 32675944, 2020). "In addition, ZRANB2(−) + SNHG20(−) group gained the smallest tumor size and the longest survival time among all the groups." (PMID 30744670, 2019). "Meanwhile, SNHG20 knockdown inhibited the proliferation and tumour growth of OSCC cells." (PMID 30394668, 2019). "Notably, statistical analysis revealed that high SNHG20 expression levels in NSCLC were significantly correlated with larger tumor size (P=0.012), lymph node invasion (P=0.005) and TNM stage (P=0.008)." (PMID 28981099, 2017). "Moreover, correlation analysis using 20 paired NSCLC and adjacent non-tumor lung tissues showed that SNHG20 expression was inversely correlated with P21 expression in NSCLC tissues." (PMID 28981099, 2017). "Conversely, ectopic expression of SNHG20 induced malignant tumor cell behaviors." (PMID 28981099, 2017). "In addition, SNHG20 has a tendency to correlate with tumor size." (PMID 33089952, 2020). "lncRNA SNHG20 was upregulated in OSCC, and its knockdown inhibited OSCC cell proliferation and tumor growth." (PMID 35874897, 2022). "For has-miR-331-3p, SNHG20 leads to the activation of HER2 in tumors by interacting with it, enhancing tumor cell invasion and migration." (PMID 35371342, 2022). "LINC01605, SNHG20, LUCAT1, and ZNF337-AS1 had significantly high expression in tumor tissues, while MEG9, LINC01082, and DICER1-AS1 had high expression in ADJ tissues." (PMID 34544413, 2021). "In xenograft mice in vivo assay, SNHG20 knockdown suppressed the tumour growth of OSCC‐CSC (CSC‐SCC15), including tumour volume and weight." (PMID 30394668, 2019). "ZRANB2(−), SNHG20(−) and ZRANB2(−) + SNHG20(−) group had the smaller tumor size and longer survival time than ZRANB2(−)-NC + SNHG20(−) group." (PMID 30744670, 2019). "Importantly, β-catenin knockdown attenuated the SNHG20-mediated increase in DLBCL cell proliferation in vitro and tumour growth in vivo." (PMID 38886753, 2024). "Furthermore, overexpression of SNHG20 activates the PI3K/Akt/mTOR signaling pathway, contributing to tumor progression and stemness in glioblastoma." (PMID 36770654, 2023). "The lncRNA FTX was downregulated and the lncRNA SNHG20 was upregulated in NAFLD-related HCC tumor tissues, and FTX supplement and SNHG20 silencing inhibited the conversion of NAFLD to HCC, which prompted out interest in explorng its potential as a future HCC risk predictor." (PMID 36979495, 2023). "The mechanism was reported to involve the SNHG20/miR-6516-5p/secretoglobin family 2A member 1 (SCGB2A1) signalling pathway: SNHG20 suppressed miR-6516-5p level, which negatively modulated SCGB2A1, a positive regulator of tumour cell activity that is elevated in PCa." (PMID 33968736, 2021). "Additionally, the expression of SNHG20 and ROCK1 was remarkably suppressed, but the expression of miR-148a was strikingly increased in the tumor tissues from sh-SNHG20 group." (PMID 34836544, 2021).
tumor (continued). "Likewise, the clinicopathologic analyses manifested that patients with the high SNHG20 expression levels had increased occurrence probability of advanced TNM stage, large tumor size, positive lymph node metastasis, high tumor stage, and poorly differentiated grade." (PMID 32675944, 2020).